CD4 (CD4 molecule)
Diseases named in the same sentence as CD4 in open-access papers (continued):
Sharing a sentence is not in itself a finding about the gene and the disease.
COVID-19 (continued). "On the other hand, the profound immunodeficiency depicted by B lymphopenia and abnormal CD4/CD8 ratio present in TET patients with GS, could substantially impact severity and disease course of COVID-19." (PMID 38898390, 2024). "Therefore, the evaluation of TIM3+CD39+CD4+CD3+CD45+, as well as CD39+CD45+, has high power for the prognostication of COVID-19 patients on hospital admission." (PMID 38793691, 2024). "The expression levels of CD4+, a T cell marker, and CD68+, a macrophage marker, were significantly higher in the COVID-19 group than in control samples, suggesting that T lymphocytes and macrophages drive the pathological changes associated with SARS-CoV-2 infection." (PMID 39057113, 2024). "Furthermore, after the COVID-19 vaccination, IFN-γ+CD4+ T cells numerically dominated over IFN-+CD8+ T cells, similar to what was observed after SARS-CoV-2 infection and COVID-19 vaccination in non-human primates." (PMID 39568586, 2024). "Age ≥40 years, CD4 counts <200 cells/μL, ≥2 comorbidities, and incomplete/nonreception of the SARS-CoV-2 vaccine increased the risk of severe COVID-19 among migrants." (PMID 38221982, 2024). "Furthermore, a study found increased levels of activated CD4+ and CD8+ T-cells after 3 months of recovery from mild, moderate, and severe COVID-19." (PMID 38482000, 2024). "The results demonstrated that ICU COVID-19 patients showed lower levels of infiltration in T cells CD8, T cells CD4 memory activated, T cells regulatory (Tregs), NK cells resting, Monocytes, Macrophages M2 and Eosinophils, Meanwhile, higher levels of infiltration in neutrophils." (PMID 38600309, 2024). "IL6ST, which encodes the signal-transducing receptor gp130, was more uniformly expressed throughout the investigated cell types and its expression was significantly downregulated in neutrophils and upregulated in monocytes, CD4+ and CD8+ T cells and B cells from severe COVID-19 patients." (PMID 39835136, 2024). "However, LC patients displayed persistent immune alterations, including reduced T cell subsets (CD4, CD8, Tregs) and switched memory B cells, similar to COVID-19 patients." (PMID 39845978, 2024). "Besides CD134 and CD137 functional markers, we recently assessed the expression of additional activation and cytotoxicity markers by CCCs/SARS-CoV-2-cross-reactive CD4+ and CD8+ T cells from COVID-19 patients and healthy individuals." (PMID 38605956, 2024). "Surprisingly, in our spatial transcriptomics data, we did not see an increase of T cells in islets of COVID-19 samples, although both CD4 and CD8 T cells contribute to T1D development." (PMID 39232561, 2024). "As CD4+ TEM cells developed, the expression of both LAG3 and SLFN5 in COVID-19 was upregulated." (PMID 39337460, 2024). "Meanwhile, CD4+ cells and PAB were protective factors (OR<1) for COVID-19 elderly patients." (PMID 39416623, 2024). "Similarly, the α-CCCs/SARS-CoV-2 cross-reactive epitopes were strongly cross-recognized by IFN-γ+CD4+ T cells (SFCs>50) and CD8+ T cells from both unexposed pre-pandemic healthy individuals (UPPHI) and unvaccinated asymptomatic COVID-19 patients." (PMID 38605956, 2024). "Low but substantial frequencies of specific CD4+ and CD8+ T cells were detected in the blood of COVID-19 patients compared to healthy donors, both at baseline and on day 7, thus highlighting the onset of an anti-viral response in COVID-19 patients." (PMID 39896810, 2024). "Interestingly, when analyzing absolute numbers of CD4+ T cell subpopulation, we observed significantly increased numbers of TM and EM convCD4+ T cells expressing CD74 in the blood of COVID-19 patients (Supplement 3A), despite their lymphopenia." (PMID 37946732, 2023). "In a recent study, patients with COVID-19 were reported to have increased levels of CD4+PD1+CD57+ exhausted T cells as compared to non-symptomatic individuals." (PMID 36679947, 2023). "Different COVID-19 vaccine combinations did not generate different S-specific CD4+ or CD8+ T cell responses." (PMID 37234151, 2023).
COVID-19 (continued). "Immunological studies in recovered COVID-19 patients revealed that a combination of SARS-CoV-2-specific antibodies, memory B cells and CD4 and CD8 T cells are likely to be beneficial in minimizing COVID-19 severity and to achieve clinical short-term protection." (PMID 37404819, 2023). "Induction of antigen-specific CD4+CD154+CD137+CXCR5+ pTFH cells by the COVID-19 vaccine was higher in CVID seroresponder than in non-seroresponder." (PMID 36932291, 2023). "Our findings demonstrated that lymphocyte counts and CD3+ and CD4+CD8+ subsets were significantly lower in COVID-19 patients, particularly in the non-survivor group." (PMID 36836679, 2023). "As poor CD4-count leads to lower cross-reactive antibodies (regardless of viral load), people living with HIV (especially those with poor clinical status) appear more vulnerable to COVID-19 and should be prioritized for vaccination." (PMID 37090738, 2023). "Furthermore, several studies have reported the presence of lymphopenia (especially in CD4+ and CD8+ T cells) in COVID-19 patients." (PMID 36986336, 2023). "COVID-19 patients and those with liver injury exhibit clinical manifestations, including elevation in ALT, AST, GGT, bilirubin, TNF-α, and IL-6 and reduction in the levels of CD4 and CD8." (PMID 36671484, 2023). "The formation of an inflammatory control mechanism by the increase in PD-1-positive T and non-T cell subpopulations as well as regulatory CD4 T cells in patients with COVID-19 across the whole observation period is suggested." (PMID 37034572, 2023). "COVID-19 vaccines based on mRNA, adenovirus vector, or inactivated virus platforms and validated for use in humans also induce SARS-CoV-2-specific CD8+ and CD4+ T-cell responses that resemble the timing of responses following natural infection." (PMID 37513709, 2023). "To investigate whether SARS-CoV-2 infects CD4+ T cells in vivo, we purified CD4+ and CD8+ T cells from peripheral blood cells of COVID-19 patients." (PMID 37523305, 2023). "Inactivated virus COVID-19 vaccines, such as CoronaVac and Covaxin (BBV152), generate relatively weak CD4 T-cell responses and a mixture of Th1 and Th2 cells, but Covaxin may be more effective due to substantial Th1 and TFH-cell responses." (PMID 37112761, 2023). "CD247, CD2, CD40LG, and KLRB1 displayed a positive correlation with CD8+ T cells and CD4+ T cells in both COVID-19 and sepsis cases, while LCN2 and RETN showed a negative correlation." (PMID 37822934, 2023). "CD4+ Foxp3+ regulatory T cells (TREGS) are a central component of immune regulation, as humans are reliant on TREGS expressing Foxp3 gene, which has been extensively investigated in the context of cancer regulation and COVID-19." (PMID 36851285, 2023). "Our research examined the correlation between ALC, CD4+ cells, and CD8+ cells in COVID-19 patients." (PMID 37377785, 2023). "We found that the CDR3 sequences enriched in COVID patients had overlap among mild, moderate, and severe patients, while there was almost no overlap in CDR3 enrichment between healthy donors and COVID-19 patients in both CD4 T cell and CD8 T cell datasets." (PMID 36670287, 2023). "We saw that Tregs as a proportion of CD4 were not changed in acute COVID-19 patients but appeared to be reduced at the follow-up stage." (PMID 36669118, 2023). "Moderate correlation between percentages of CD4+RORgt+ and CD3+IL-17+ T cells in terminal stage of COVID-19 implicate that expression of RORγt transcriptional factor may induce production of IL-17 in T cells." (PMID 37057213, 2023). "Moreover, another study showed that there were decreased proportions of CD4+CD73+ and CD8+CD73+ in the circulating blood of severely infected COVID-19 individuals." (PMID 38139439, 2023). "In addition to antibodies, both CD4+ T helper (Th) cells and CD8+ cytotoxic T lymphocyte (CTL)-specific responses are key factors against viral infections like COVID-19." (PMID 38005968, 2023).
COVID-19 (continued). "Other authors have also highlighted CD4+ T-cell peripheral depletion and altered functionality as negative prognostic markers for severity and survival in COVID-19." (PMID 37568402, 2023). "Similarly, another group demonstrated that severe COVID-19 patients exhibited higher frequencies of CD39+CD4+ T-cells and diminished frequencies of CD73+CD4+ and CD73+CD8+ T-cells in comparison with mild COVID-19 patients and healthy controls." (PMID 37818368, 2023). "In the context of COVID-19 pulmonary infiltrations, histopathological evidence gathered from 60 autopsies demonstrated that CD8+ T-cells were abundant, whereas the CD4+ T cell presence was low in the pulmonary interstitium, in contrast to the cases of control patients without infection." (PMID 37568402, 2023). "Our results indicated that patients with moderate–severe forms of COVID-19 had a significantly reduced population of lymphocytes, CD4+ T cells, CD8+ T cells (only numeric), and CD4+/CD8+ index compared with patients who presented with mild forms of COVID-19 (p < 0.05)." (PMID 37046564, 2023). "Increased expression of CXCR5 and ICOS on SARS-CoV-2-specific CD4 T cells in mild to severe COVID-19 patients with acute infection has been reported, but none of the studies tested cTfh functionality directly." (PMID 37061513, 2023). "Given the results above, as severe (stage IV) COVID-19 is outlined by increment of proinflammatory Th1 cytokines, IL-12 and IFN-γ, and Th17 cytokines, IL-17 and IL-23, we later on examined transcriptional activity of CD4+ and CD8+ T cells." (PMID 37057213, 2023). "Overall, current literature shows that COVID-19 severity and outcomes may be worse and immune responses to infection or vaccination lower in PLWH with poor CD4 + T-cell counts and/or uncontrolled HIV viremia." (PMID 36680700, 2023). "Upon SARS-CoV-2 infection, frequencies of CD74-expressing CD4+ T cells from COVID-19 patients with a mild disease course were not altered in comparison to healthy individuals." (PMID 37946732, 2023). "The number of circulating CD4 + and CD8 + T cells decreases significantly in COVID-19." (PMID 37460909, 2023). "In the context of COVID-19, CD38 expression is widely induced across CD8, CD4, Treg, and plasma cells, suggesting that CD38 expression across these disparate populations may either be driven by a central factor or interaction between these cell types." (PMID 36669118, 2023). "In addition, we also evaluated the levels of neutralizing antibodies over time and according to CD4 count at the end of PVC, which is the marker currently accepted as a primary correlate of protection against COVID-19." (PMID 38140145, 2023). "Additionally, CD4+ and CD8+ T cells from subjects who had COVID-19 exhibit a higher expression of the programmed cell death marker PD1 when compared with control subjects." (PMID 37753077, 2023). "Therefore, studying the immune response characteristics of CD4+ and CD8+ T cells, and their interactions in antiviral immunity, is crucial in designing effective COVID-19 therapeutic and vaccine strategies." (PMID 37705735, 2023). "It has been reported that COVID-19 vaccination positively affects CD4 counts and viral markers in PLWH, as indicated by increased CD4 counts after vaccination and an increased percentage of patients with HIV-RNA < 50 copies/mL after the second and third vaccinations." (PMID 38140668, 2023). "The increase of PD-1-positive subpopulations of T and non-T cells and regulatory CD4 T cells in patients with COVID-19 during the observation period suggests the development of an inflammation control mechanism." (PMID 37034572, 2023). "COVID-19 Generates Atypical CTLA-4high Effector and CXCR4high Naïve Conventional CD4+ T Cells." (PMID 36669118, 2023). "Here, we show for the first time that CD62L+ CD4+ T cells are increased in ICU patients with severe COVID-19 compared to non-severe hospitalized COVID-19 patients." (PMID 36817450, 2023).
COVID-19 (continued). "In contrast, CD22 was minimally expressed on CD4+ Tconv cells of control individuals, patients with acute COVID-19, and patients with MIS-C, and it did not correlate with Notch1 expression in these cells." (PMID 36282598, 2023). "There were significant differences in neutrophil, lymphocyte, eosinophil (Eos), C-reactive protein (CRP), D-dimer, lactate dehydrogenase (LDH), glucose, IL-6, ferritin, CD4 + T cell, CD4+/CD8 + T cell, CD8 + T cell, and B cell counts in the serum of the four COVID-19 patient groups (P < 0.05)." (PMID 37705107, 2023). "The differentiation of CD4+ T cells, activated by the interaction of IL-23 with TYK2/Jak2, occurs with the participation of IL-6, IL-1β and TGF-β, which is extremely important in the context of the cytokine storm in COVID-19." (PMID 37896870, 2023). "Indeed, cellular immunity is known to play a crucial role in SARS-Cov2 infection, as specific CD4 and CD8 responses have been identified in healthy COVID-19-recovered individuals, as well as in recovered agammaglobulinemic patients." (PMID 37316832, 2023). "The percentage of CD4- and CD8-expressing EVs were higher in the moderate COVID-19 patients (p = 0.0077 and p = 0.0062, respectively) and CD8-expressing EVs were higher in the severe COVID-19 patients (p = 0.0051) compared to the HCs." (PMID 36982991, 2023). "Also, reduced frequencies of CD4+ and/or CD8+ effector and central memory T cells have been observed in severe compared to mild COVID-19." (PMID 36793739, 2023). "Based on univariate analysis and a priori assumptions, multivariate modeling was implemented to assess the relationship between (a) COVID-19 and (b) key host factors and the humoral immune repertoire, adjusting for age, natal sex, GBD region, nadir CD4, HIV viral load (VL)." (PMID 36805331, 2023). "In post-COVID-19 samples collected 14 days after the day of documented infection, a marked increase in reactivity against all four tested SARS-CoV-2 antigens was observed, predominantly within the CD4+ T cell compartment." (PMID 37901229, 2023). "Four out of the 17 (23.5%) COVID-19/PLWH patients with a CD4 count ≤200 cells/μL died, compared to none of the 15 (with outcome data) and a CD4 count >200 cells/μL." (PMID 37646024, 2023). "Comparison of cellular immunity in pregnant and nonpregnant women with COVID-19 revealed prototypical activation patterns of classical αβ CD4+ and CD8+ T cells, while NK and γδ T cell activation was similar during acute infection, indicating a typical COVID-19 innate response, as observed by others." (PMID 37036008, 2023). "In the umbilical cord blood samples of children whose mothers tested positive for COVID-19 4–6 weeks before delivery (subgroup 1), the CD4+CCR7+ T cells increased with a concomitant decrease in the proportion of naive CD4+ T cells compared with the control group (p = 0.016)." (PMID 37445296, 2023). "Moreover, CD38 and HLA-DR were differentially expressed by CD4+ and CD8+ T cell subsets in BALF-MC and in PBMC among SARS-CoV-2-infected patients who died from COVID-19 (p < 0.05)." (PMID 36986364, 2023). "Thirteen cases were described in a recent review, of which only one had HIV (CD4+ cell count not reported) and 92% received steroids for severe COVID-19." (PMID 37233294, 2023). "In accordance with the given assumptions, the aim of the study was to establish the years of life, presence of sepsis and MODS, values of additional factors with confirmed prognostic significance and number of peripheral CD4+ and CD8+T lymphocytes in critically ill patients with COVID-19." (PMID 37780864, 2023). "Patients with MIS-C, but not children or adults with acute COVID-19, demonstrated increased Notch1 expression on circulating CD4+ Tregs and Tconv cells, all of which declined precipitously following antiinflammatory therapy." (PMID 36282598, 2023). "However, further studies investigating the role of CD4+TRMs in type 2 airways against SARS-CoV-2 and COVID-19 would be noteworthy." (PMID 36851616, 2023).
COVID-19 (continued). "In summary, SARS-CoV-2-specific CD4+ and CD8+ T-cells could be detected in the peripheral blood of patients 3 months after mild, moderate, and severe COVID-19." (PMID 37310006, 2023). "About 20-60% of COVID-19-naïve individuals have circulating CD4+ T cells that can cross-recognize SARS-CoV-2 spike and nonspike antigens, what brings important implications for SARS-CoV-2 primary infection and vaccination." (PMID 37388738, 2023). "When controlling for prior COVID-19, the association of frailty with vaccine-specific AIM+CD8+ and AIM+CD4+ T cells remained non-significant (p = 0.17 and p = 0.12, respectively)." (PMID 36650551, 2023). "A greater proportion of PWH who had not received a COVID-19 vaccine also had no CD4 count measurements (27% vs. 9%) or HIV VL (21% vs. 4%) measurements during the study period." (PMID 37996521, 2023). "The breadth of CD4+ and CD8+ T cell responses was also significantly different between S and N proteins, suggesting different contributions of N and S protein-specific T cells for COVID-19 control." (PMID 37428088, 2023). "Given that a low CD4+/CD8+ ratio is predictive of adverse clinical outcomes in PLWH, it could serve as a potential tool for evaluating the course of COVID-19 in these patients, thus providing an additional option in risk stratification." (PMID 36839516, 2023). "The unavailability of detailed information such as viral load, CD4 count, and specific anti-retroviral therapy regimen limits our ability to draw definitive conclusions regarding the clinical interaction between HIV and COVID-19." (PMID 37509543, 2023). "To assess the correlation of immune responses to memory T cell subsets between HC and LC individuals, we analyzed the phenotype of CD4+ T cells, CD8+ T cells and memory T cell subsets between the time of symptom onset of COVID-19 using a multicolor flow cytometer." (PMID 37766091, 2023). "Conversely, SARS-CoV-2-specific central memory CD4 and effector memory CD8 T cells were detected in the peripheral blood of COVID-19 patients after 14 days of infection, leading to a proposition that induction of cell mediated immune responses by COVID vaccines is equally important." (PMID 36814238, 2023). "S17 and S18, respectively) showed potential trends toward increasing spike-specific CD8+ T cell degranulation response (CD107a+), higher frequencies of spike-specific CD4+ IL-2+ T cells, and higher frequencies of spike-specific CD4+ IFN-γ+ T cells in COVID-19 convalescent patients (P = 0.036)." (PMID 37824612, 2023). "Furthermore, immune responses to SARS-CoV-2 that generate coordinated CD4 and CD8 T cell-based immunity have been shown to correlate with favorable outcomes in COVID-19 patients." (PMID 37313411, 2023). "Another investigation reported that there were no significant changes in CD4+ T cell subsets amongst COVID-19, convalescence, and healthy control people." (PMID 38004749, 2023). "In contrast, we found a shared decrease in naïve and central memory CD4+ T cells and naïve CD8+ T cells in both COVID-19 and HIV-1+ patients, suggesting that viral infection is polarizing both CD4+ and CD8+ T cells toward cytotoxicity programs, especially following SARS-CoV-2 infection." (PMID 36992700, 2023). "TGFB1 was increased in multiple CD3+ subsets including CD4+ TEMRA, CD8+ TEMRA, CD8+ EM, non-VD2 gamma-delta, and VD2 gamma-delta T cells following Foralumab treatment when compared to both healthy controls and untreated COVID-19 subjects." (PMID 36881624, 2023). "Also, apoptosis pathways enrichment in the COVID-19 patients mainly in CD8+ TEM, CD8+ TCM, and activated CD4+ T cells reminds us of lymphopenia, which reduces the number of T cells compared to healthy and recovered individuals." (PMID 37886355, 2023). "The number of CD4+ CXCR6+ T cells was reduced in the blood of patients with severe COVID-19 compared to those with a negative viral load." (PMID 37762093, 2023).